MALAT1 (metastasis associated lung adenocarcinoma transcript 1)
Diseases named in the same sentence as MALAT1 in open-access papers (continued):
Sharing a sentence is not in itself a finding about the gene and the disease.
lung cancer (continued). "For instance, preclinical studies have shown that targeted inhibition of lncRNA MALAT1 by ASOs can effectively reduce lung cancer metastasis in mouse models." (PMID 40746614, 2025). "For instance, the identification of MALAT1 in tumor tissues of lung cancer, ovarian cancer and prostate cancer can be used as an auxiliary diagnostic method." (PMID 41316360, 2025). "The selectivity and specificity of MALAT1-ASO were validated in lung cancer and epidermal carcinoma cell lines (A549, A431, PC9GR, and PC9) using cellular fluorescence and flow cytometry." (PMID 40597438, 2025). "For instance, the lncRNA Malat1 has been proposed as a predictive biomarker for lung cancer metastasis." (PMID 40861865, 2025). "MALAT1 levels were also shown to be higher in lung cancer patients with BrM, and functional studies indicate that MALAT1 promotes migration and metastasis of brain-metastatic lung cancer cells by inducing EMT." (PMID 40016470, 2025). "MALAT1 has been described to promote lung cancer, and its high expression is typically a marker of poor prognosis." (PMID 40452889, 2025). "For example, the lncRNA MALAT1 has been shown to interact with specific proteins that promote lung cancer metastasis." (PMID 40861865, 2025). "Research on lncRNAs in lung cancer is also receiving increasing attention, with many lncRNAs such as MALAT1 and HOTAIR being abnormally expressed in lung cancer tissues." (PMID 41394878, 2025). "Specifically, inhibiting MALAT1 expression reduces the migration and invasion abilities of lung cancer cells, suppressing tumor metastasis." (PMID 41394878, 2025). "MALAT1 is one of the lncRNAs that contribute to metastasis and resistance to tyrosine kinase inhibitors in lung cancer." (PMID 40783798, 2025). "Originally, MALAT1 was discovered in non‐small cell lung cancer and was determined as a prognostic marker for metastasis in these patients." (PMID 38517409, 2024). "Our comprehensive study demonstrated that in AA populations the upregulation of MALAT1 plays a crucial role in the development and progression of lung cancer." (PMID 38791954, 2024). "MALAT-1 plays a key role in the initiation and advancement of lung cancer, according to comprehensive studies on the subject." (PMID 38511067, 2024). "Intriguingly, E-cadherin and vimentin expression increased in this study, concluding that MALAT-1 promoted brain metastasis of lung cancer cells by inducing EMT." (PMID 38201661, 2024). "Our current study, employing xenograft mouse models, cell lines, and human plasma and tissue samples, found that MALAT1 upregulation affects both tumor growth and progression in lung cancer within the AA population." (PMID 38791954, 2024). "For example, Oct4 transcriptionally activates the expression of NEAT1 and MALAT1 to accelerate lung cancer progression." (PMID 38430256, 2024). "MALAT1 is a metastasis-related lncRNA that was first found in non–small cell lung cancer; it can promote tumor invasion and metastasis by facilitating epithelial-to-mesenchymal transition and inducing angiogenic factors." (PMID 38818308, 2024). "A notable example of an lncRNA is metastasis-associated lung adenocarcinoma transcript 1 (MALAT1), also known as nuclear-enriched abundant transcript 2 (NEAT2), initially identified in nonsmall cell lung cancer (NSCLC)." (PMID 38791545, 2024). "Key lncRNAs such as NEAT1, TUG1, MALAT1, HOTAIR, and GAS5 demonstrate a crucial role in lung cancer progression and serve as powerful prognostic and diagnostic biomarkers." (PMID 39201688, 2024). "Given the role of MALAT1 in promoting cell proliferation and metastasis, particularly in lung cancer, targeting this lncRNA represents a promising therapeutic strategy." (PMID 38791954, 2024). "For instance, MALAT1 knockout cells were created using CRISPR-Cas9 technology, which revealed the role of MALAT1 in the regulation of alternative splicing and its contribution to lung cancer metastasis." (PMID 39448589, 2024).
lung cancer (continued). "As a result of its abundance and abnormal expression, MALAT1 lncRNA plays a critical role in the development of several malignancies, including lung cancer colorectal cancer, and bladder cancer." (PMID 38517388, 2024). "This study's main finding emphasizes MALAT-1's molecular relevance to lung cancer cell proliferation and gefitinib resistance." (PMID 38511067, 2024). "We also assessed the levels of miR-206 in lung cancer tissue samples, which had been previously analyzed for MALAT1 and MCP-1 expression." (PMID 38791954, 2024). "MALAT1 is aberrantly expressed in pancreatic cancer, lung cancer, breast cancer, colorectal cancer, gastric cancer, nasopharyngeal carcinoma, hepatocellular carcinoma, and osteosarcoma." (PMID 38339342, 2024). "One study used ASO and the nucleus-targeting TAT peptide conjugated to Au nanoparticles (ASO-Au-TAT NPs) to target MALAT-1 in lung cancer." (PMID 38201661, 2024). "MALAT1: MALAT1 is a highly conserved lncRNA implicated in COPD pathogenesis and lung cancer metastasis." (PMID 39201688, 2024). "By modulating miR-206 and MCP-1, MALAT1 contributes to increased cell proliferation and cancer progression of lung cancer in AA patients." (PMID 38791954, 2024). "For instance, lung cancer has high expression levels of MALAT1, which encourages metastasis and adds to treatment resistance." (PMID 39325172, 2024). "One such example is MALAT1, which has been extensively studied in the context of lung cancer metastasis." (PMID 39201688, 2024). "MALAT1 levels were found to be elevated in both lung tumor tissues and plasma samples from AA lung cancer patients." (PMID 38791954, 2024). "For AAs, the most accurate prediction for lung cancer was achieved by combining three lncRNAs (MALAT1, PVT1, and SNHG1) with smoking pack-years." (PMID 38791954, 2024). "In lung cancer, MALAT1 promotes metastatic spread, EMT, and resistance to chemotherapy and targeted therapies, highlighting its prognostic value and therapeutic potential in advanced-stage disease." (PMID 39201688, 2024). "Consistently, lung cancer cell lines derived from AA patients exhibited higher levels of MALAT1 in both cells and their supernatants compared to cell lines developed from WA lung cancer patients." (PMID 38791954, 2024). "Elevated MALAT1 highly expression has been detected in lung cancer, endometrial stromal sarcoma, hepatocellular carcinoma, tongue squamous cell carcinoma, breast cancer and pancreatic cancer." (PMID 38517388, 2024). "Recent reports revealed that long non-coding RNA (lncRNA) of metastasis-associated lung adenocarcinoma transcript 1 (MALAT1) plays a crucial role in tumorigenesis and metastasis development in lung cancer." (PMID 38517388, 2024). "Our study highlights the significant role of lncRNAs, particularly MALAT1, in the racial disparities observed in lung cancer." (PMID 38791954, 2024). "Lipid nanoparticles have shown effective in delivering siRNAs that target the long non-coding RNA MALAT1 in preclinical models of lung cancer." (PMID 39325172, 2024). "In this section, we will explore the mechanistic role of MALAT-1 in various types of cancer, including gastrointestinal cancers, reproductive system cancers, and lung cancer." (PMID 38511067, 2024). "Through these interactions, MALAT1 modulates the expression of genes involved in various aspects of lung cancer progression, including metastasis." (PMID 39201688, 2024). "MALAT-1 silencing inhibited the invasion and metastasis of a highly invasive subline of brain-metastatic lung cancer cells in vitro and in vivo." (PMID 38201661, 2024). "The primary objective of the study was to investigate the association between the expression levels of three lncRNAs (MALAT1, HOTAIR, and AFAP1‐AS1) and lymph node metastasis (LNM) of lung cancer." (PMID 39725668, 2024).
lung cancer (continued). "Forced MALAT1 expression led to enhanced growth and invasiveness of lung cancer cells, both in vitro and in vivo, accompanied by elevated levels of MCP-1, CD68, CD163, CD206, and KI67." (PMID 38791954, 2024). "We utilized MALAT1-targeting antisense oligonucleotides (MALAT1 ASOs) in our in vivo study to evaluate their therapeutic potential for lung cancer treatment." (PMID 38791954, 2024). "Patients with lung cancer have lower levels of MALAT1 in their blood compared to healthy individuals, with an area under the receiver operator curve of 0.718." (PMID 37250901, 2023). "For example, in lung cancer, the stability of MALAT1 was increased by its hyper m6A modification level induced by METTL3." (PMID 37029420, 2023). "In lung cancer, systemic administration of Malat1 ASO in nude mice yielded a marked reduction in the colonization of patient-derived lung cancer cells in the lungs, as compared to non-targeting controls." (PMID 37370745, 2023). "MALAT1 has been found to act as a ceRNA for miR‐185‐5p in lung cancer, and RhoA is a target gene of miR‐185 in human colorectal cells." (PMID 37395157, 2023). "In order to directly assess the effect of MALAT1 genotypes on the expression of MALAT1 and miR-328 in lung cancer patients, carcinoma lung tissue samples were harvested from lung cancer patients to evaluate MALAT1 and miR-328 expression." (PMID 36934373, 2023). "Knockdown of MALAT1 and overexpression of miR-101-3p increase cisplatin sensitivity in lung cancer cells." (PMID 36778005, 2023). "lncRNA MALAT1, one of the first discovered lncRNAs, has been widely studied in breast cancer metastasis, lung cancer, colorectal cancer and other tumor diseases." (PMID 37872392, 2023). "For instance, MALAT1 was suggested to be involved in multiple tumors; inhibition of the well-studied lncRNA was found to prevent lung cancer metastasis." (PMID 36902227, 2023). "For lncRNA MALAT1, its aberrant expression has been found in multiple cancers, including lung cancer, hepatocellular carcinoma, colorectal cancer, gastric cancer." (PMID 36813772, 2023). "Given its various roles in lung cancer, the authors insisted on the need for additional studies on MALAT1 mechanisms, and their confirmation as potential biomarkers through further research." (PMID 37250901, 2023). "It is notable that the effect of MALAT1 on cell function was uncovered instudies using the A549 lung cancer cell line." (PMID 37538803, 2023). "MALAT1 is a well-known long noncoding RNA in lung cancer, and its expression contributes to malignancy." (PMID 37910161, 2023). "To determine the oncogenic function of MALAT1 in lung cancer and identify genes interacting with MALAT1, we performed cell-based assays, transcriptome analyses, and bioinformatic analyses." (PMID 37667226, 2023). "For example, lncRNA MALAT1 increases cisplatin resistance in lung cancer by enhancing the expression of MRP1 and MDR1 by activating the STAT3 pathway." (PMID 36778005, 2023). "As MALAT1 can be detected in whole blood, has the potential to be a useful biomarker for identifying and facilitating the treatment of lung cancer." (PMID 37250901, 2023). "The size of primary lung tumor was observed, and no obvious difference was found in respect to the size of primary lung cancer in patients with different MALAT1 genotypes." (PMID 36934373, 2023). "Quantitative real-time PCR was performed to examine the expression of MALAT1 and miR-328 in the peripheral blood samples collected from lung cancer patients with different MALAT1 genotypes." (PMID 36934373, 2023). "In lung carcinoma, lncRNA MALAT1 downregulation suppressed lung carcinoma progression by regulating miR-491-5p." (PMID 36855431, 2023). "In a study with the lung cancer cell lines LLC and A549, lung carcinoma cell-derived exosomes suppress DC costimulatory molecule expression, inflammatory response and promote DCs autophagy via MALAT1, a transcript that stimulates the AKT/mTOR pathway." (PMID 37915578, 2023).
lung cancer (continued). "Malat1, a long non-coding RNA that is crucial for mouse lung development and is overexpressed in a variety of lung cancers." (PMID 35391793, 2022). "It is noted that MALAT1 confers acquired malignant phenotypes of lung cancer cells, as well as enhanced drug resistance for NSCLC cells by cooperation with microRNAs." (PMID 35046387, 2022). "Metastasis-associated lung adenocarcinoma transcript 1 (MALAT1) and colon cancer-associated transcript 2 (CCAT2) are acted as biomarkers in patients with lung cancer." (PMID 36357869, 2022). "Our findings were parallel to the findings of previous studies where MALAT1 promoted drug resistance in cancer cells via modulating STAT3 activation in lung cancer and enhanced FUT4 fucosylation by sponging miR-26a/26b involving PI3K/AKT pathway." (PMID 35281907, 2022). "Detection of MALAT1 in peripheral blood or urine samples can be used for the early diagnosis of lung cancer and prostate cancer, respectively." (PMID 35907897, 2022). "LncRNAs have become the key regulatory factors in development and progression of lung cancer, functioning as oncogenes (e.g., MALAT1, HOTAIR, H19 and ANRIL) or tumor suppressors (e.g., MEG3, GAS5, and TUG1)." (PMID 34976181, 2022). "In fact, numerous molecules, and their corresponding signaling pathways, have been validated as targets of MALAT1 in lung cancer." (PMID 35454102, 2022). "MALAT1, which was first identified in lung cancer, plays an important role in the pathogenesis of various human diseases, such as cancer and autoimmune and inflammatory diseases." (PMID 34489556, 2022). "A study has shown that increased MALAT1 expression promotes brain metastasis in lung cancer and correlates with patient survival." (PMID 35693013, 2022). "The results of the preceding studies suggest that MALAT1 is a metastatic biomarker for lung cancer and has the potential to be used therapeutically to prevent metastasis." (PMID 36419933, 2022). "Previous studies have shown that the expression level of MALAT1 in lung cancer is higher than that in normal lung tissues, and the overall survival rate of lung cancer patients with high expression of MALAT1 is lower." (PMID 35402492, 2022). "Current study suggests these two SLs to be the promising agents for overcoming paclitaxel resistance in A549 lung cancer cells via MALAT1/STAT3/FUT4 axis." (PMID 35281907, 2022). "MALAT1 suppresses lung cancer by regulating MDSCs which, in turn, modulate immune responses that inhibit tumors and other diseases." (PMID 36419933, 2022). "Another study had confirmed that MALAT1 plays a role in lung cancer metastasis by regulating the expression of related target genes rather than alternative splicing by establishing a MALAT1 gene knockout model." (PMID 35311148, 2022). "A 1,000-fold knockdown of MALAT1 in human lung cancer cells via zinc finger nuclease technology impairs cancer cell migration, and blocking the lncRNA MALAT1 pathway regulates EMT and combats tumor metastasis." (PMID 36419933, 2022). "These RNA biomarkers have been reported to be associated with lung cancer, including CK19 and PCTK1 mRNAs, MALAT1 lncRNA, and miR21 and miR155 miRNAs." (PMID 35678691, 2022). "The results reveal that three types of lncRNAs (MALAT1, H19, and CUDR) can be used as the diagnostic indices of lung cancer-MPE." (PMID 35651679, 2022). "The lncRNA, metastasis-associated lung adenocarcinoma transcript 1 (MALAT1), was initially discovered in non-small cell lung cancer and was associated with lung cancer metastasis." (PMID 35706417, 2022). "The coexpression of OCT4, NEAT1 and MALAT1 can also be used to predict the prognosis of lung cancer patients." (PMID 35907897, 2022). "MALAT1 is involved in multiple biological functions and overexpressed in many cancers, such as liver cancer, lung cancer, renal cancer, gastric cancer." (PMID 35645836, 2022). "The lncRNA, metastasis-associated lung adenocarcinoma transcript 1 (MALAT1), was first identified in lung cancer." (PMID 35910856, 2022).
lung cancer (continued). "In view of the current high mortality and morbidity of lung cancer, many mechanism studies also had shown that MALAT1 was related to the occurrence, development and prognosis of lung cancer." (PMID 35928715, 2022). "A study on the correlation between OCT4 and lncRNAs expression in 124 lung cancer patients found that overexpression of MALAT1 in lung cancer cells promoted cell proliferation." (PMID 36420141, 2022). "By targeting the miR-197-3p/p120 signaling axis, MALAT1 increases lung cancer cell resistance to cisplatin and cellular resistance to tetracycline, gefitinib, and paclitaxel." (PMID 35706002, 2022). "This competition between MALAT1 and MCL1 causes a decrease in MCL1 expression and a consequent increase in drug resistance in lung cancer." (PMID 34489556, 2022). "As MALAT1 can be detected in whole blood, it can be readily used to identify and facilitate the treatment of lung cancer." (PMID 36419933, 2022). "Using ANX-bead capturing and reverse transcription and quantitative PCR, we detected significantly higher levels of CK19 mRNA, MALAT1 lncRNA, and miR155 miRNA in the plasma of lung cancer patients." (PMID 35678691, 2022). "In lung cancer, MALAT1 overexpression inhibits the tumor suppressor PSF and regulates the amplification of tumor-suppressing MDSCs." (PMID 36419933, 2022). "MALAT1 expression has been detected in both in situ lung carcinoma and metastatic lymph node tissues, but its levels are higher in lung carcinoma than in lymph node metastases." (PMID 36419933, 2022). "MALAT1, an early discovered lncRNA, is found to be highly expressed in many cancers such as lung cancer, gastric carcinoma, and breast cancer." (PMID 35005241, 2021). "LncRNA MALAT1 has been found to be upregulated in multiple cancers, including lung cancer and hepatoma." (PMID 33809929, 2021). "An RT-PCR assay was performed to examine the MALAT1 expression levels in cancer tissues obtained from lung cancer patients, the MALAT1 RNA levels were higher in tumor tissues than in adjacent tissues." (PMID 34257576, 2021). "Increased expression of the lncRNA MALAT1 correlates with poor prognosis in lung cancer, whereas reduced MALAT1 expression leads to reduced lung cancer cell motility, an indicator of lowered metastatic ability." (PMID 34842768, 2021). "A study on lncRNA MALAT1 indicated that MALAT1 directly affected MDSCs differentiation in lung cancer." (PMID 35047506, 2021). "The results of this study showed that MALAT1 knockdown decreased UBE2C expression at mRNA and protein levels and UBE2C contributed to the proliferation and colony formation abilities, which were regulated through MALAT1, of lung cancer cells." (PMID 34257576, 2021). "To confirm this phenomenon, we also investigated the distribution of MALAT1 in lung cancer cell lines A549 and H1299 under normoxia, because MALAT1 was reported to be a highly abundant nuclear transcript in these cells." (PMID 34012919, 2021). "Another case is that LncRNA MALAT1 has shown to be a key regulator of the metastatic phenotype of lung cancer cells." (PMID 34461605, 2021). "In particular, they showed that three lncRNAs (MALAT1, H19, and CUDR) have potential as diagnostic markers in lung cancer-associated MPE." (PMID 34199799, 2021). "Malat1 is a highly conserved nuclear lncRNA initially identified as a predictor of lung cancer metastasis." (PMID 33815273, 2021). "In conclusion, knockdown of MALAT1 which is upregulated in lung cancer, inhibited the proliferation, colony formation, migration and invasion abilities of lung cancer by sponging miR-491-5p to downregulate UBE2C expression." (PMID 34257576, 2021). "Some ncRNAs have been targeted in lung cancer treatment studies as well, including miR-21 and MALAT1." (PMID 33803619, 2021). "Several studies report the abundant expression of MALAT1 in multiple cancers such as lung cancer, bladder cancer, breast cancer, colorectal cancer and others." (PMID 33441968, 2021).